RNU6-358P (RNA, U6 small nuclear 358, pseudogene)
Gene: Small nuclear RNA gene on chromosome 5 (31,820,564 to 31,820,638, reverse strand). Ensembl gene ENSG00000252373.
Homologues: Orthologues: chimpanzee U6 (99% identical), macaque U6 (97% identical), rabbit U6 (85% identical), dog U6 (83% identical), dog U6 (81% identical), guinea pig U6 (80% identical), dog U6 (75% identical), mouse Gm23754 (69% identical), rat LOC120101970 (68% identical). Paralogues in human: RNU6-33P (91% identical), RNU6-39P (91% identical), RNU6-1 (89% identical), RNU6-11P (89% identical), RNU6-15P (89% identical), RNU6-16P (89% identical), RNU6-2 (89% identical), RNU6-25P (89% identical), RNU6-37P (89% identical), RNU6-3P (89% identical), RNU6-43P (89% identical), RNU6-47P (89% identical), and 1284 more.